RPF1 (ribosome production factor 1 homolog)
Description:
May be required for ribosome biogenesis.
Synonyms: BXDC5
Tractability: Small molecule: a structure with a bound ligand is known. PROTAC: ubiquitination databases record sites on it; its protein half-life has been measured.
Gene: Protein-coding gene on chromosome 1 (84,479,257 to 84,498,352, forward strand). Ensembl gene ENSG00000117133.
Subcellular location: Nucleus, nucleolus
Subcellular location (Human Protein Atlas): Nucleoli
Gene Ontology:
Molecular function: protein binding; RNA binding; rRNA binding; rRNA primary transcript binding
Biological process: maturation of 5.8S rRNA; maturation of LSU-rRNA; rRNA processing
Cellular component: nucleolus; preribosome, large subunit precursor
Genetic constraint (gnomAD): Loss-of-function variants: 13 observed, 14.16 expected, observed/expected ratio (o/e) 0.92, 90% interval 0.6 to 1.46. The upper end of that interval is the gene's LOEUF score, 1.46, which puts it in group 6 of 6, group 1 being the genes least tolerant of losing a copy. Missense variants: 191 observed, 190.63 expected, observed/expected ratio (o/e) 1, 90% interval 0.89 to 1.13. Synonymous variants: 60 observed, 71.58 expected, observed/expected ratio (o/e) 0.84, 90% interval 0.68 to 1.04.
Homologues: Orthologues: chimpanzee RPF1 (100% identical), mouse Rpf1 (95% identical), dog RPF1 (95% identical), rat Rpf1 (94% identical), pig RPF1 (94% identical), guinea pig RPF1 (93% identical), tropical clawed frog rpf1 (78% identical), zebrafish rpf1 (71% identical), Caenorhabditis elegans F44G4.1 (50% identical), Drosophila melanogaster CG6712 (45% identical). Paralogues in human: IMP4 (26% identical).
Diseases named in the same sentence as RPF1 in open-access papers:
RPF1 is named in the same sentence as 5 diseases in open-access papers, as found by Europe PMC text mining. Sharing a sentence is not in itself a finding about the gene and the disease. The quoted sentences say what the papers report.
glioblastoma (1 paper, 2022). The most malignant astrocytic tumor (WHO grade IV). "Eight genes associated with glioblastoma prognosis were identified based on LASSO analysis: RPS10, RPS11, RPS19, RSL24D1, RPL39L, EIF3E, NUDT5, and RPF1." (PMID 36733371, 2022).
cancer (1 paper, 2023). A tumor composed of atypical neoplastic, often pleomorphic cells that invade other tissues. "For the remaining genes, OR10A3, RPF1, KΑTNA1, and CES4A, in our risk score model, no specific relationship to cancer had been reported yet, further exploration should be carried out for their roles in the prognosis in DLBCL patients." (PMID 36816541, 2023).
infection (1 paper, 2015). The state of being infected such as from the introduction of a foreign agent such as serum, vaccine, antigenic substance or organism. "Finally, we show that the mixed rpf-1/rpf-2 population presents synergism in DSF production and virulence capacity in an in vivo infection model." (PMID 26284046, 2015).
RPF1 also shares sentences with these, for which no sentence is quoted: Insulin resistance (1 paper); ischaemic stroke (1).